ENTPD1 (ectonucleoside triphosphate diphosphohydrolase 1)
Diseases named in the same sentence as ENTPD1 in open-access papers (continued):
Sharing a sentence is not in itself a finding about the gene and the disease.
periodontitis (4 papers, 2022 to 2024). An acute or chronic inflammatory process that affects the tissues that surround and support the teeth. "C3, C4A, and ENTPD1 are closely associated with periodontitis severity and may regulate periodontitis occurrence and development." (PMID 36457739, 2022). "In contrast to the healthy group, the periodontitis group had higher levels of ENTPD1, TLR4, LY96, and PRF1 expression and lower levels of P2RX7 expression, according to the qPCR data." (PMID 39555084, 2024). "Five hub ICD-related genes (ENTPD1, TLR4, LY96, PRF1 and P2RX7) were identified for the construction of a diagnostic model for periodontitis." (PMID 39555084, 2024). "Five key genes associated with ICD (ENTPD1, TLR4, LY96, PRF1 and P2RX7) may be diagnostic biomarkers of periodontitis and future therapeutic targets." (PMID 39555084, 2024). "In line with the findings of the validation set, our findings demonstrated that ENTPD1, TLR4, LY96, PRF1 were elevated in periodontitis patients while P2RX7 expression was decreased." (PMID 39555084, 2024).
type 1 diabetes (4 papers, 2019 to 2024). "Positive correlations between low CD39/ENTPD1 levels and disease activity has been observed in type 1 diabetic children, suggesting a potential compromise in Treg function." (PMID 30691212, 2019).
acute GVHD (3 papers, 2019 to 2023). "GMSCs that were treated with an ENTPD1 inhibitor (POM-1) prior to transfer demonstrated a reduced therapeutic effect in acute GVHD." (PMID 37895880, 2023).
chordoma (3 papers, 2022 to 2023). Chordomas are rare malignant tumors arising from embryonic remnants of the notochord in axial skeleton. "Despite the elevated proportion of Tregs observed in recurrent chordomas, the cells exhibited significant expression of TIGHT, CTLA4, PDCD1, ENTPD1 and HAVCR2, indicating the immunosuppressive nature of Tregs." (PMID 37784253, 2023).
papillary thyroid carcinoma (3 papers, 2021 to 2025). "We used 388 samples with papillary thyroid carcinoma in cBioPortal database to explore the genetic alteration of ENTPD1." (PMID 34465393, 2021). "The sub-type of THCA patients influenced the ENTPD1 expression, and higher expression was observed in classical and follicular thyroid papillary carcinoma." (PMID 34465393, 2021).
Parkinson disease (3 papers, 2023 to 2025). A progressive degenerative disorder of the central nervous system characterized by loss of dopamine producing neurons in the substantia nigra and the presence of Lewy bodies in the substantia nigra and locus coeruleus. "The GSEA results suggest that ENTPD1, SERPINA1, and TACSTD2 may be involved in the occurrence and development of PTC by jointly regulating the spliceosome, Parkinson’s disease, and cytokine–cytokine receptor interaction pathways." (PMID 40520228, 2025).
psoriasis (3 papers, 2019 to 2024). An autoimmune condition characterized by red, well-delineated plaques with silvery scales that are usually on the extensor surfaces and scalp. "In addition to the cytokines noted above such as IL17F (0.967), and CXCL13 (0.325), this set contained identified psoriasis-specific genes with less established functional roles, such as ARHGEF12 (0.303), ENTPD1 (0.628), LAYN (0.122) and HAVCR2 (0.560)." (PMID 35958578, 2022).
acrodermatitis (2 papers, 2018 to 2022). An inflammatory skin condition affecting children. "It is also suggested that zinc deficiency causes a decrease in Langerhans cells that express ENTPD1/CD39 leading to severe acrodermatitis." (PMID 36555806, 2022). "Zinc masks dermatitis, whereas severe acrodermatitis is caused by decreased Langerhans cells that highly express ENTPD1/CD39 44,45." (PMID 30271993, 2018).
dementia (2 papers, 2020 to 2024). Loss of intellectual abilities interfering with an individual's social and occupational functions. "The phenotypic transformation from homeostatic microglia towards reactive microglia in dementia pathologies is associated with TREM2, HLA-DRA, ENTPD1 (CD39), CD80 (B7-1), CD86 (B7-2), CCR5, CD274, ITGAX (CD11c), TIMD4 and MRC1." (PMID 33113879, 2020).
depression (2 papers, 2022 to 2024). "Entpd1, also known as CD39, is a microglia signature gene and has been shown to promote depression behavior in mice." (PMID 36253828, 2022).
epilepsy (2 papers, 2020 to 2024). A brain disorder characterized by episodes of abnormally increased neuronal discharge resulting in transient episodes of sensory or motor neurological dysfunction, or psychic dysfunction. "The chromosomal position of human CD39 (ENTPD1)/ecto-apyrase (10g23.1 to q24.1) is collocated with the gene related to partial human epilepsy with audiogenic symptoms (10q.22 to 24)." (PMID 33262686, 2020). "Fourteen epilepsy-associated genes were identified as potential targets of ADORA2A in epilepsy, and four key genes including NT5E, ENTPD1, ADA, and ADK were mainly involved in the “negative regulation of neuron death” and “purine nucleoside biosynthetic process” biological processes." (PMID 33262686, 2020).
Hodgkins lymphoma (2 papers, 2019 to 2025). A heterogeneous group of malignant lymphoid neoplasms of B-cell origin characterized histologically by the presence of Hodgkin and Reed-Sternberg (HRS) cells in the vast majority of cases. "Our findings demonstrate a significant and robust correlation between ENTPD1 and Hodgkin lymphoma, suggesting that the inhibition of ENTPD1 may also exhibit antitumor effects in this disease." (PMID 40360443, 2025). "Furthermore, our study revealed a significant correlation between ENTPD1 (ectonucleoside triphosphate diphosphate hydrolase‐1) and Hodgkin lymphoma as well as other unspecified types of non‐Hodgkin lymphoma." (PMID 40360443, 2025). "Our findings exhibited significant correlations in Hodgkin's lymphoma between CD247, CMTM6, CD25, ENTPD1, MBL2, and CD40." (PMID 40360443, 2025).
thrombotic disorders (2 papers, 2015 to 2021). "Future works will be aimed to investigate the ENTPD1-mediated protection against the coagulation and thrombotic disorders in xenotransplantation as well as the immunosuppressive effects derived by the ENTPD1/E5NT-mediated production of adenosine." (PMID 26513260, 2015). "These evidences suggest that ENTPD1 could address the coagulation and thrombotic disorders that still limit the graft survival." (PMID 26513260, 2015).
undifferentiated pleomorphic sarcoma (2 papers, 2022). An undifferentiated soft tissue sarcoma characterized by the presence of a pleomorphic malignant cellular infiltrate. "Differential gene expression between radioresponsive myxoid liposarcoma (MLPS) and more radioresistant undifferentiated pleomorphic sarcoma (UPS) indicated UPS contained higher transcript levels of a number of immunotherapy targets (CD73/NT5E, CD39/ENTPD1, CD25/IL2RA, and 4–1BB/TNFRSF9)." (PMID 35558159, 2022).
Zinc deficiency (2 papers, 2018 to 2022). A deficiency of the essential metal Zinc; an essential cofactor for many enzymes. "For example, both high expression of TNAP, ENPP1, ENPP3, and NT5E/CD73 and low expression of ENTPD1/CD39 increase the susceptibility of cells to the effects of zinc deficiency on extracellular adenine-nucleotide metabolism." (PMID 30271993, 2018). "The quantification of each adenine nucleotide and adenosine hydrolyzed from ATP revealed that the effects of zinc deficiency varied depending on the cell type, which can be attributed to the distinct expression pattern and level of ENTPD1/CD39, ENPP1, ENPP3, NT5E/CD73, TNAP, PAP, and their isozymes." (PMID 30271993, 2018).
adult T-cell leukemia/lymphoma (1 paper, 2021). A peripheral (mature) T-cell neoplasm linked to the human T-cell leukemia virus type 1 (HTLV-1), adult T-cell leukemia/lymphoma is endemic in several regions of the world, in particular Japan, the Caribbean, and parts of Central Africa. "It has demonstrated that adult T-cell leukemia/lymphoma (ATLL) cells expressed ENTPD1 at a high rate, which contributed ATLL cells to escape anti-tumor immunity through the extracellular ATPDase-Adenosine cascade." (PMID 34465393, 2021).
Autosomal recessive spastic paraplegia type 64 (1 paper, 2019). "After NGS sequencing and cosegregation analysis, the variant c.401T>G (p.M134R) in the ENTPD1 gene, for which both sisters were homozygous, was identified as a mutation responsible for a complicated form of HSP, autosomal-recessive spastic paraplegia type 64 (SPG64)." (PMID 30652007, 2019).
endometrial disorder (1 paper, 2018). A non-neoplastic or neoplastic disorder that affects the endometrium. "No relevant studies focus on the relationship of Entpd1, Fam50a, and Brms1 to endometrial disorders, and further studies are needed." (PMID 30322386, 2018).
gastritis (1 paper, 2019). Inflammation of the stomach. "Adenosine generation by ENTPD1/CD39 and CD73 on Treg and memory T-cells, strongly inhibits effector T-cell immunity, as shown in vitro and in experimental models of H. felis-induced gastritis in vivo." (PMID 30941139, 2019).
hepatoblastoma (1 paper, 2024). Hepatoblastoma (HB) is a malignant hepatic tumor and is the most common pediatric liver cancer. "Hepatoblastoma tumor cells exhibited upregulation of purine metabolism through enhanced expression of ENTPD1, PDE4C, PDE5A, and PAPSS1." (PMID 39684755, 2024).
ocular hypertension (1 paper, 2017). Abnormally high intraocular pressure. "We characterize this novel model to show that ocular hypertension results in mild retinal dysfunction, RNFL thinning and a reduction in RGC density along with an increased Entpd1 gene expression." (PMID 28239332, 2017).
primary biliary cholangitis (1 paper, 2019). Primary biliary cholangitis (PBC) is a chronic and slowly progressive cholestatic liver disease of autoimmune etiology characterized by injury of the intrahepatic bile ducts that may eventually lead to liver failure. "Patients affected by primary biliary cholangitis exhibit dramatic phenotypic alterations in CD8+ Tregs, as reflected by increased levels of CD127 and lower CD39/ENTPD1 expression that correlate with lower responsiveness to IL-10." (PMID 30691212, 2019).
schizophrenia (1 paper, 2024). A major psychotic disorder characterized by abnormalities in the perception or expression of reality. "In the comparison including all schizophrenia and control subjects, the mRNA expression levels of ENT1, ENT2, ENTPD1, ENTPD3, and NT5E were not significantly different between the two sexes." (PMID 39404420, 2024). "In an enriched population of ACC pyramidal neurons, the mRNA expression levels of ADK, ENT1, ENT2, ENTPD1, ENTPD3, and NT5E were assessed between individuals with schizophrenia and sex- and age-matched non-psychiatrically ill control subjects." (PMID 39404420, 2024). "In the present study, we assayed the transcript expressions of ADK, ENT1, ENT2, ENTPD1, ENTPD3, and NT5E in an enriched population of pyramidal neurons in the postmortem ACC tissue of patients diagnosed with schizophrenia compared with non-psychiatrically ill sex- and age-matched patients." (PMID 39404420, 2024).
Spastic paraplegia (1 paper, 2018). Complete loss of the ability to move the lower limbs accompanied by spasticity of the lower limbs. "Case E has a nonsynonymous de novo single nucleotide variant (SNV) in ENTPD1, which is recessive and involved in spastic paraplegia (OMIM 615683)." (PMID 28771244, 2018).
T/NK cell lymphomas (1 paper, 2025). "In mature T/NK cell lymphomas, a significant association was observed between CD247 and ENTPD1." (PMID 40360443, 2025).
tumor (973 papers, 2009 to 2026). "We demonstrated that CD39 deficiency in MC38 tumor-bearing CD39KO (Entpd1 null) mice decreases tumor growth." (PMID 41668741, 2026). "CD39 (ENTPD1) is a rate-limiting enzyme in adenosine metabolism, leading to the view that CD39 is associated with immune suppression because of the inhibitory function of adenosine in tumor immunity." (PMID 41943833, 2026). "In the tumor setting, ENTPD1 deletion caused a reduction in tumor growth and tumor formation by inhibiting angiogenesis in an in vivo mouse model." (PMID 41575692, 2026). "CD39, encoded by ENTPD1, is an ectoenzyme that converts extracellular ATP to adenosine and has been implicated in Tregs and tumor-specific exhausted T effector cells." (PMID 40906156, 2025). "ENTPD1 is implicated in the production of adenosine, which exerts immunosuppressive effects within the tumor microenvironment." (PMID 40458414, 2025). "Previous studies have shown that the conversion of ATP to AMP is primarily catalysed by Ectonucleoside triphosphate diphosphohydrolase 1 (ENTPD1/CD39), a widely studied ATPase, which is expressed in tumor-associated immune cells." (PMID 38755598, 2024). "The increased level of the enzyme encoded by Entpd1 (also known as CD39), which catalyzes the rate-limiting step of the conversion of extracellular ATP to adenosine in the tumor microenvironment, has been associated with metastasis." (PMID 36430209, 2022). "Inhibition of ENTPD/1CD39 in murine cancer models induces anticancer activity and ENTPD1/CD39 deficient mice demonstrated a reduction in tumor growth." (PMID 36051466, 2022). "Cycling cells were predominantly T cells and mostly expressed the tissue residency marker CD103 (ITGAE) together with CD39 (ENTPD1) which has been associated with tumor specificity." (PMID 36253784, 2022). "CD39 (ENTPD1), a molecule associated with chronic immune cell stimulation, was proven to be a marker of tumor-infiltrating CD8+ T cells." (PMID 33747255, 2021). "Furthermore, the CD39 encoding gene ENTPD1 is among the most highly upregulated genes in CD8+ T cells isolated from tumor tissue, along with other T cell exhaustion marker encoding genes (HAVCR2, CTLA4, TIGIT)." (PMID 37648263, 2023). "Interestingly, NSA identified ENTPD1/CD39, a gene signal associated with an immunosuppressive tumor microenvironment, was most highly predictive of Vigil responsiveness." (PMID 36051466, 2022). "In the current study, Vigil treated patients with baseline elevated tumor expression of ENTPD1/CD39 was associated with a significantly improved response compared to those patients with tumors with low expression and to those with high tumor expression treated with placebo." (PMID 36051466, 2022). "Checkpoint, cytotoxicity, and TRM signature scores, as well as ENTPD1 expression, were also higher in pTRC from the tumor, and stemness scores were lower in tumor pTRC." (PMID 39900903, 2025). "Ectonucleoside triphosphate diphosphohydrolase-1 (ENTPD1), also known as CD39, is an ectonucleotidase that generates adenosine, thereby suppressing the anti-tumor activities of CD4 and CD8 T-cells, as well as NK cells." (PMID 40236693, 2025). "The production of extracellular adenosine in the tumor microenvironment is linked to poor patient outcomes and is driven by high expression of the ectonucleotidases CD39 (ENTPD1) and CD73 (NT5E)." (PMID 40519286, 2025). "Other upregulated genes included NR3C1, NMB, and COTL1, which are coordinately expressed with PDCD1, CXCL13, and ENTPD1 by tumor infiltrating CD4+ T cells." (PMID 40956619, 2025). "A hallmark of T cell exhaustion is the sustained expression of markers such as Tox, Ctla4, Entpd1, Pdcd1, and Havcr2, many of which were enriched in the tumor-infiltrating subset (Cluster 5)." (PMID 40229241, 2025).
tumor (continued). "This is largely due to increased expression and activity of two key ectoenzymes, CD39 (ENTPD1) and CD73 (NT5E), on the surface of tumor cells, cancer-associated fibroblasts, endothelial cells, regulatory T cells (Tregs), and certain myeloid subsets." (PMID 41514547, 2025). "Cancer-related genes, such as CD70, VEGFA, and ENTPD1 (also known as CD39), which are reportedly associated with immune suppression, tumor proliferation, immune escape, and drug resistance, exhibited increased expression in patients in the neural-high group." (PMID 41147013, 2025). "Analyzing CD8 TILs, we focused on the expression of ENTPD1 (CD39), an indicator of the tumor-associated response." (PMID 40164596, 2025). "Among these molecules, ENTPD1 (CD39) stands out due to its well-documented role in tumor immunosuppression." (PMID 40636690, 2025). "Our findings indicated that immune checkpoints (PDCD1, ENTPD1 and TIGIT), the T-cell exhaustion state-associated transcription factor TOX, and the gene DDX58 (transcriptional protein RIG-I) are co-expressed in tumour-infiltrating CD8+ T cells (Fig. EV1A–D)." (PMID 39322862, 2024). "Based on previous studies and the observation of local TCR clone expansion, the expression of ITGAE/ENTPD1 was considered to serve as a general marker for tumor‐reactiveness also for these CD4+/CD8+ T cells." (PMID 38582099, 2024). "CD39, encoded by ENTPD1, is present on various cell types, including tumor cells, tumor-specific CD4 and CD8 T cells, endothelial cells, fibroblasts, and cells of myeloid lineage." (PMID 38785789, 2024). "mRNA expression of target genes Entpd1 in tumor and Dcaf7 in liver was reduced indicating biological activity of INT-1B3." (PMID 39007281, 2024). "A hallmark of T cells exhaustion is persistent expression of markers including Tox, Ctla4, Entpd1, Pdcd1, Havcr2, and others, many of which were expressed in the tumor TEX subset." (PMID 38496632, 2024). "In addition, flow cytometry (FCM) analysis of CD39 (encoded by ENTPD1) in HGSC samples revealed a greater expression in tumor-infiltrating Tregs compared to CD4+ and CD8+ effector T cells, indicating that Tregs may account in a large part for ENTPD1 expression." (PMID 39013886, 2024). "These tumor-specific upregulated genes included inhibitory receptors, such as ENTPD-1 49 and PDCD1, as well as effector molecules, such as GZMK and IFNG, all involved in antitumor activity." (PMID 38948071, 2024). "Inhibition of two ectoenzymes important for the metabolism of extracellular nucleotides, CD73 (ecto-5’nucleotidase) and CD39 (ectonucleoside triphosphate diphosphohydrolase-1), greatly improved antitumor immune responses, thereby slowing tumor growth." (PMID 38786066, 2024). "For example, overexpression of the ectonucleoside triphosphate diphosphohydrolase 1 (ENTPD1) in metastatic tumor cells hydrolyze extracellular ATP into AMP to convert it to adenosine in hypoxia condition caused by HIF-1." (PMID 37190251, 2023). "CD39 (ENTPD1) is a key enzyme responsible for degradation of extracellular ATP and is upregulated in the tumor microenvironment (TME)." (PMID 37219538, 2023). "The genes positively associated with NLR (CD39 (ENTPD1), PTEN, MYD88, MMP9 and LDH) are involved in processes of immunosuppression, inflammation and tumor-promoting activity." (PMID 37684649, 2023). "The genes positively associated with NLR [CD39 (ENTPD1), PTEN, MYD88, MMP9 and LDH] have immunosuppression, inflammation and tumor-promoting activity." (PMID 37684649, 2023). "Current research indicated that ENTPD1 (CD39) can suppress the anti-tumor activity of T cells and NK cells, which suggests its potential for cancer therapy." (PMID 36676763, 2023). "ENTPD1/CD39 is expressed in the tumor microenvironment, in vessels, B cells, NK cells, dendritic cells, monocytes, macrophages, regulatory T cells and monocyte-derived suppressor cells." (PMID 37684649, 2023).